DNMT3B (DNA methyltransferase 3 beta)
Diseases named in the same sentence as DNMT3B in open-access papers (continued):
Sharing a sentence is not in itself a finding about the gene and the disease.
thymoma (5 papers, 2013 to 2020). A neoplasm arising from the epithelial cells of the thymus. "The T allele and TT genotype of DNMT3B-579G>T were associated with increased risk of developing thymoma in Italian patients with myasthenia gravis (MG)." (PMID 31565203, 2019). "In the present study we investigated if a common polymorphism (-579G>T: rs1569686) in the promoter of the DNMT3B gene coding for the DNA methyltransferase 3B, an enzyme that mediates DNA methylation, increases the risk to develop MG or MG-associated thymomas." (PMID 24260492, 2013). "Present results suggest that the DNMT3B-579T allele might contribute to the risk of developing thymoma in MG patients, particularly in homozygous TT subjects." (PMID 24260492, 2013). "Our study suggests that the presence of the DNMT3B-579T allele might represent a risk factor for the development of MG-associated thymomas, particularly in carriers of the homozygous TT genotype, while it probably does not have effect on other MG subtypes." (PMID 24260492, 2013). "The goal of the present study was to investigate if a common polymorphism (-579G>T: rs1569686) in the promoter of the DNMT3B gene coding for the DNA methyltransferase 3B, one of the key de novo enzymes mediating DNA methylation, increases the risk to develop MG or MG-associated thymomas." (PMID 24260492, 2013). "Similarly, a SNP in the promoter of DNMT3B, namely −579G>T, was associated with TAMG, overall suggesting a contribution of de novo DNMTs in thymomas." (PMID 27999265, 2016). "In our cohort, DNMT1 and DNMT3B do not show different methylation levels among different tissues, so we cannot hypothesize the involvement of the methylation of these genes in thymoma-associated myasthenia gravis pathogenesis." (PMID 27999265, 2016).
viral infection (5 papers, 2018 to 2023). "DNMT3B expression was significantly up-regulated in tumor tissues and this up-regulation was significantly associated with viral infection." (PMID 34946098, 2021). "Actually, viral infection, chronic inflammation, and oxidative stress have been shown to affect DNMTs expression in HCC.Viral oncoproteins, such as the HCV core and the HBx protein of HBV, upregulate DNMT1 and DNMT3B." (PMID 32514254, 2020). "Here, we found that DNMT1 rather than DNMT3a or DNMT3b was involved in modification of DNA methylation during H5N1 virus infection; this is because expression of DNMT1 was inhibited upon virus infection, whereas that of the other two DNMTs changed little." (PMID 29717211, 2018).
Anxiety (4 papers, 2014 to 2023). Intense feelings of nervousness, tension, or panic often arise in response to interpersonal stresses. "After being fed a diet supplemented with methyl donors ad libitum, adult mice reversed the alteration of gene expression of Dnmt3a, Dnmt3b, Grin2b and Gabar2, but anxiety-like behavior became elevated." (PMID 25144567, 2014).
atherosclerosis (4 papers, 2020 to 2023). A disease characterized by the build-up of fatty material and calcium deposition in the arterial wall resulting in partial or complete occlusion of the arterial lumen. "We found that Dnmt3b silencing ameliorated atherosclerosis was associated with increasing the Treg levels caused by reducing the methylation levels of Foxp3-TSDR and upregulated the expression of Foxp3 in Tregs." (PMID 35422896, 2022). "DNMT3b accelerates atherosclerosis and may be associated with forkhead box P3 hypermethylation status in human peripheral blood regulatory T cells." (PMID 38031118, 2023). "DNMT3b accelerated atherosclerosis, and may be associated with FOXP3 hypermethylation status in regulatory T cells." (PMID 35422896, 2022). "We demonstrated that DNMT3b accelerated atherosclerosis may be associated with FOXP3-TSDR hypermethylation, which is responsible for the subsequent down-regulation of FOXP3 expression and inhibition of Treg function." (PMID 35422896, 2022). "It has been found that DNMT3b expression is associated with the development of atherosclerosis." (PMID 35422896, 2022). "Thus, we hypothesize that DNMT3b-mediated hypermethylation of FOXP3 in Tregs would be one of the underlying mechanisms of atherosclerosis." (PMID 35422896, 2022). "FOXP3 is an immunoregulatory DNA-binding protein that is vital in the development and function of Tregs, and the DNMT3B-mediated downregulation of FOXP3 induces atherosclerosis." (PMID 37947606, 2023). "In ApoE−/− mice, Dnmt3b silencing attenuated atherosclerosis by decreasing lesion size and macrophage content while increasing collagen and smooth muscle cell content." (PMID 38031118, 2023). "DNMT3B also accelerates atherosclerosis by hypermethylating the forkhead box P3 (FOXP3) promoter and decreasing FOXP3 expression in regulatory T cells (Tregs), which are cells that normally prevent inflammation and autoimmunity." (PMID 37947606, 2023). "DNMT3b can also reduce the expression of fibroblast growth factor 2 and promote atherosclerosis by increasing DNA methylation in endothelial cells." (PMID 35422896, 2022). "Inhibition of scavenger receptor class B member 1 expression induced by DNMT3b accelerated atherosclerosis in foam cells." (PMID 35422896, 2022). "It showed that Dnmt3b silencing attenuated atherosclerosis, including decreased lesion size and macrophage content and increased collagen and smooth muscle cells content in ApoE−/− mice." (PMID 35422896, 2022). "Because proliferation of FOXP3+ Tregs can be induced by DNA methyltransferase inhibitor such as AZA and EGCG, the epigenetic regulation of the FOXP3 gene via DNMT3b shows potential therapeutic targets for atherosclerosis." (PMID 35422896, 2022). "DNMT3b was found to be involved in atherosclerosis by regulating methylation levels of targeted genes in multiple atherosclerosis-related cell types." (PMID 35422896, 2022). "It has been found that DNMT3b reduces the expression of genes by increasing the methylation level of the related genes, which affects the development of atherosclerosis." (PMID 35422896, 2022). "Previous studies have shown that DNA methyltransferase 3b (DNMT3b) may play an important role in atherosclerosis." (PMID 35422896, 2022). "This study aimed to establish the regulatory role of DNMT3b in the development of atherosclerosis." (PMID 35422896, 2022). "The present study provides a new insight into the aggravating role of DNMT3b in atherosclerosis." (PMID 35422896, 2022). "In the present study, we found direct evidence that DNMT3b is involved in atherosclerosis." (PMID 35422896, 2022). "The present study identifies that DNMT3b expression promotes atherosclerosis." (PMID 35422896, 2022). "Thus, we suppose that DNMT3b participated in accelerating atherosclerosis may be through regulating methylation levels of Foxp3-TSDR in Tregs and suppressing Treg function." (PMID 35422896, 2022).
atherosclerosis (continued). "Our study provides the first direct evidence that DNMT3B-mediated CREG gene hypermethylation is a novel mechanism that contributes to endothelial dysfunction and atherosclerosis development." (PMID 32067910, 2020). "In human atherosclerotic arteries, there was a negative correlation between DNMT3B and CREG expression levels, indicating blocking CREG methylation may represent a novel therapeutic approach to treat ox-LDL-induced atherosclerosis." (PMID 38031118, 2023).
B-cell lymphomas (4 papers, 2012 to 2021). "The effect of overexpression of DNMT3B7, a C-terminally truncated, catalytically inactive splice variant of DNMT3B, has recently been analyzed in a mouse model of B cell lymphoma." (PMID 22563479, 2012). "Our results confirmed the activation of DNMT1 by HIV in vivo, and reported for the first time a marked up-regulation of DNMT3a and DNMT3b in HIV-positive aggressive B-cell lymphomas." (PMID 25705251, 2014). "DNMT3B likely plays a role in pathogenesis of various hematologic malignancies as genetic alterations were identified in cutaneous T-cell lymphomas (CTCLs) and B-cell lymphomas (BCLs)." (PMID 33450231, 2021). "Knockout of DNMT3B accelerates the initiation of MYC-driven T- and B-cell lymphoma in mouse models (EμSRα-tTA;tet-o-MYC and Eμ-MYC), while increased DNA methylation of DNMT3B targets delays leukemogenesis." (PMID 29100357, 2017).
diabetic nephropathy (4 papers, 2018 to 2025). "Gondaliya et al26 found that miR29b might effectively target DNMT3B, DNMT1 and DNMT3A contributing in the development of diabetic nephropathy in renal proximal tubular cells." (PMID 33484504, 2021).
head and neck cancer (4 papers, 2013 to 2020). A primary or metastatic malignant neoplasm affecting the head and neck. "In conclusion, our meta-analysis suggested that DNMT3B −149C/T polymorphism was not related to overall cancer risk, whereas there was an association between DNMT3B −149C/T polymorphism and head and neck cancer risk under heterozygote comparison and dominant model." (PMID 25433949, 2015). "Thus, our findings reveal that DNMT3B -283T/C is associated with cancer risk, whereas DHFR 19-pb ins/del and TYMS 28-bp tandem repeat polymorphisms have a protective effect against head and neck cancer in relation to that in the control group." (PMID 33369477, 2020). "Here, we aimed to investigate the association of polymorphisms DNMT3B -149C/T (rs2424913), DNMT3B -283T/C (rs6087990), DNMT3B -579G/T (rs2424909), DHFR 19-pb ins/del (rs70991108), SHMT1 1420C/T (rs1979277), and TYMS 28-bp tandem repeat (rs34743033) with the risk of head and neck cancer." (PMID 33369477, 2020). "To date, the DNMT3B rs2424913 polymorphism has been demonstrated to be a risk factor of lung, breast, and head and neck cancers and age of onset of hereditary nonpolyposis colorectal cancer (CRC)." (PMID 23666104, 2013).
Hodgkins lymphoma (4 papers, 2018 to 2021). A heterogeneous group of malignant lymphoid neoplasms of B-cell origin characterized histologically by the presence of Hodgkin and Reed-Sternberg (HRS) cells in the vast majority of cases. "DNMT1 and DNMT3B expression was shown to be downregulated in EBV-infected lymphoblastoid cells and Hodgkin’s lymphoma cell lines, which is distinct from that observed for EBVaGC and EBV-positive NPC." (PMID 29438328, 2018).
Hyperglycemia (4 papers, 2016 to 2023). An increased concentration of glucose in the blood. "Dot blot and immunofluorescence analyses showed that DNMT3B knockdown efficiently abolished hyperglycemia-induced global accumulation of 5mC/5hmC." (PMID 37101286, 2023). "DNMT3B knockdown in H9c2 cells treated with high glucose confirmed the role of this methyltransferase enzyme in hyperglycemia-induced increase in the DNA methylation levels." (PMID 37101286, 2023). "Hyperglycemia also increased 5mC and 5hmC levels in H9c2 cells, which was normalized by DNMT3B knockdown or AKG supplementation." (PMID 37101286, 2023). "In agreement with above reports, our RNA-seq data showed that Dnmt1 was decreased and Dnmt3b was increased consistently in all three stem/progenitor cell-derived EVs subjected to hyperglycemia." (PMID 32942572, 2020). "Our study also demonstrated that the de novo methyltransferase DNMT3B could mediate these epigenetic alterations in cardiac tissue of diabetic animals, as confirmed by in vitro knockdown of DNMT3B in H9c2 cells, which prevents hyperglycemia-induced accumulation of 5mC and 5hmC." (PMID 37101286, 2023).
infertile (4 papers, 2012 to 2025). "In addition, significant correlations were foundbetween sperm concentration and motility as well as DNMT1 and DNMT3B proteins levels in the infertile individualswith varicocele (P<0.05)." (PMID 34455713, 2021).
ischemic stroke (4 papers, 2021 to 2024). A stroke disorder caused by obstruction of blood flow to the brain, due to thrombotic (local blood clot formation) or embolic (due to a blood clot or other material traveling from another site) event. "Silencing of lncRNA GAS5 suppressed neuron apoptosis in ischemic stroke through inhibiting DNMT3B-dependent methylation of MAP4K4." (PMID 35451738, 2022).
pneumonia (4 papers, 2020 to 2022). An acute, acute and chronic, or chronic inflammation focally or diffusely affecting the lung parenchyma, caused by an infection in one or both of the lungs (by bacteria, viruses, fungi, or mycoplasma.). "This study aimed to investigate the role of Dnmt3b in neutrophils and myeloid cells during acute pneumonia caused by P. aeruginosa." (PMID 35269409, 2022). "In conclusion, the results of the present study indicate that Dnmt3b in myeloid cells is dispensable for host defense against pulmonary P. aeruginosa infection and does not regulate the acute immune response in the airways during Pseudomonas-induced pneumonia." (PMID 35269409, 2022). "Collectively, these data suggest that Dnmt3b in myeloid cells does not play a significant role in the host response during pneumonia caused by acute P. aeruginosa infection." (PMID 35269409, 2022). "We report a thus far unknown role for bronchial epithelial cell Dnmt3b in the innate mucosal immune response to a common respiratory pathogen, providing insight into the regulatory machinery involved in reprograming of epithelial cells during pneumonia." (PMID 33793661, 2021).
renal carcinoma (4 papers, 2021 to 2022). A carcinoma arising from the epithelium of the renal parenchyma or the renal pelvis. "DNMT3B‐induced methylation of ubiquinol cytochrome c reductase hinge protein (UQCRH) contributes to renal cancer progression." (PMID 34133843, 2022). "Our results showed that UHRF1 gene expression was correlated with four methyltransferases (DNMT1, DNMT2, DNMT3A, and DNMT3B) in a variety of tumors, and KICH KIRC KIRP was positively correlated with methyltransferase, suggesting that UHRF1 may be an epigenetic driver of renal cancer type." (PMID 35656341, 2022).
Sepsis (4 papers, 2016 to 2023). Sepsis is defined as life-threatening organ dysfunction caused by a dysregulated host response to infection. "From our studies we find that epigenetic factors HDAC1, HDAC2 and DNMT3B show consistent differential expression compared to other sepsis cases, suggesting a role in disease susceptibility and pathogenesis." (PMID 28628607, 2017). "EVs from septic shock patients carried more total DNMT mRNAs and more DNMT3A+DNMT3B mRNAs than control subjects or sepsis EVs." (PMID 38343439, 2023). "It was observed that the EVs from patients in septic shock contained a higher quantity of total DNMT mRNAs, as well as DNMT3A+DNMT3B mRNAs, when compared to EVs from control subjects or individuals with sepsis." (PMID 38343439, 2023). "The levels of EV-DNMT1 and EV-DNMT3A+DNMT3B and the severity of sepsis and septic shock were found to be strongly correlated." (PMID 38343439, 2023). "Upregulated DNMT1, DNMT3a and DNMT3b, resulting in global DNA hypermethylation methylation in sepsis." (PMID 34163486, 2021). "Humans with sepsis upregulate DNMT1, DNMT3a and DNMT3b, resulting in global DNA methylation differences, 82.6% of which are suppressive hypermethylated marks." (PMID 34163486, 2021). "DNMT3B, HDAC1 and HDAC2 were significantly up regulated in other sepsis cases compared to healthy controls." (PMID 28628607, 2017).
acute lymphoblastic leukemia (3 papers, 2006 to 2023). Leukemia with an acute onset, characterized by the presence of lymphoblasts in the bone marrow and the peripheral blood. "TQ also has decreased the expression of DNMT1, DNMT3A, and DNMT3B in Jurkat T-cell acute lymphoblastic leukemia cells." (PMID 34959687, 2021). "TQ has also reduced DNMT3A, DNMT3B, and DNMT1 expression in acute lymphoblastic leukemia cells (Jurkat cells)." (PMID 37375831, 2023).
autoimmune disease (3 papers, 2013 to 2022). A disorder resulting from loss of function or tissue destruction of an organ or multiple organs, arising from humoral or cellular immune responses of the individual to their own tissue constituents. "However, a few investigations have studied the relationship of DNMT3B polymorphisms with autoimmune disease." (PMID 31565203, 2019). "Therefore, further surveys should be included to estimate the exact relevance of DNMT3B gene to the development of autoimmune disorders like MS." (PMID 31565203, 2019). "Some organ-specific autoimmune disorders were observed in these patients including hematologic autoimmunity in patients with PNP, STIM1, ORAI1, WAS, ATM, and STAT5B mutations or early-onset inflammatory bowel disease in patients with WAS, DNMT3B, and ZBTB24 mutations." (PMID 36544766, 2022).
cardiomyopathy (3 papers, 2015 to 2023). A disease of the heart muscle or myocardium proper. "Mice with cardiomyocyte-specific deletion of Dnmt3b develop cardiomyopathy with sarcomeric disarray and interstitial fibrosis." (PMID 36656640, 2023). "In a recent report, ablation of Dnmt3b in adult mice using a tamoxifen-inducible Cre recombinase led to spontaneous cardiomyopathy within two months after tamoxifen induction." (PMID 26098432, 2015).
cholangiocarcinoma (3 papers, 2021 to 2023). A carcinoma that arises from the intrahepatic biliary tree (intrahepatic cholangiocarcinoma) or from the junction, or adjacent to the junction, of the right and left hepatic ducts (hilar cholangiocarcinoma). "Furthermore, an inverse association between DNMT3B and miR-29b was observed in clinical specimens of cholangiocarcinoma." (PMID 37705098, 2023). "In this manner, miR-29b by direct targeting DNMT3B operates as an inhibitory factor for tumor growth in cholangiocarcinoma by alleviating the repressive influence of DNMT3B on CDKN2B expression." (PMID 37705098, 2023). "Accordingly, we detected an inverse correlation between miR-29b and DNMT3B expression in clinical cholangiocarcinoma specimens." (PMID 33601338, 2021). "Taken together, these results suggest that miR-29b acts as a tumor suppressor in cholangiocarcinoma by downregulating DNMT3B and promoting the expression of CDKN2B." (PMID 33601338, 2021). "In the present study, we identified DNMT3B as a downstream target of miR-29b, a fact reflected by the inverse expression pattern detected in clinical cholangiocarcinoma samples for these two genes." (PMID 33601338, 2021). "To explore the potential function of DNMT3B in cholangiocarcinoma pathogenesis, we transfected QBC939 cells with a lentiviral vector carrying the DNMT3B gene (LV-DNMT3B) or a negative control (LV-control)." (PMID 33601338, 2021). "Accordingly, a significant, inverse correlation between miR-29b and DNMT3B expression was detected through qRT-PCR analyses of clinical cholangiocarcinoma specimens." (PMID 33601338, 2021). "Therefore, our data suggest that DNMT3B acts as an oncogene in cholangiocarcinoma." (PMID 33601338, 2021). "In conclusion, our data revealed that miR-29b acts as a tumor suppressor in cholangiocarcinoma by promoting CDKN2B demethylation and transcription via suppression of DNMT3B activity." (PMID 33601338, 2021). "Meanwhile, western blot assays showed that DNMT3B levels were significantly higher in both QBC939 cells and clinical cholangiocarcinoma samples, compared to HIBEC and normal tissues, respectively." (PMID 33601338, 2021).